MTOR (mechanistic target of rapamycin kinase)
Diseases named in the same sentence as MTOR in open-access papers (continued):
Sharing a sentence is not in itself a finding about the gene and the disease.
breast cancer (continued). "It has also been shown the synergism between mTOR and FASN inhibition to induce cytotoxicity in ER/HER2-positive breast cancer cell lines." (PMID 26107737, 2015). "In breast cancers, PI3K/Akt/mTOR is the most frequently activated signaling pathway, with more than 70% of breast cancers presenting molecular alterations in one or more components of the PI3K/Akt pathway." (PMID 26703550, 2015). "The direct effects of metformin were firstly evaluated on breast cancer cells, in which AMPK was primarily activated and mammalian target of rapamycin (mTOR) signaling and protein synthesis were subsequently reduced." (PMID 26245871, 2015). "We have demonstrated that the combination of sub-optimal concentrations of PI3K/mTOR, pan-PI3K or mTOR ATP-competitive inhibitors and everolimus can achieve synergistic inhibition of the proliferation of human breast cancer cells in vitro." (PMID 26148118, 2015). "We stress again that the novel key contribution of this work is the identification of a gene module that simultaneously correlates with a poor clinical outcome in endocrine-treated ER+ breast cancer and with sensitivity to PI3K/AKT/mTOR inhibitors." (PMID 25886003, 2015). "The aim of the present study was to investigate differences between the mTOR targets S6K1 and S6K2 and their individual potentials as new clinical targets in breast cancer, as well as further explore the importance of the S6K2/4EBP1 co-expression." (PMID 26698305, 2015). "In breast cancer progression, Ras/Raf/MEK/MAPK and PI3K/Akt/mTOR signaling pathways are commonly dysregulated by the crosstalk among various growth factors and hormone receptors including HER2 and ER." (PMID 25956130, 2015). "Deregulation of the PI3K/AKT and mTOR pathways has been shown to be involved in doxorubicin- and TAM-resistance in breast cancer through the regulation of multidrug resistance proteins." (PMID 26496360, 2015). "Administration of the mTor inhibitor Everolimus has therefore been studied extensively in women with HR+, HER2+ or TNBC breast cancer." (PMID 26205886, 2015). "The mammalian target of rapamycin (mTOR), a vital component of signaling pathways involving PI3K/AKT, is an attractive therapeutic target in breast cancer." (PMID 26148118, 2015). "Combined treatment of ER positive breast cancer cells with RU-SKI 43 and either the PI3K inhibitor LY294002 or the mTOR inhibitor rapamycin resulted in a further decrease in cell proliferation compared to either drug alone." (PMID 25889650, 2015). "Activation of PI3K/mTOR signaling occurs in up to a quarter of both ER positive and HER2 positive breast cancers and several inhibitors are currently in clinical trials." (PMID 25889650, 2015). "Published data from randomised clinical trials is currently limited to mTOR inhibitors with everolimus, an mTOR inhibitor, being approved for treatment of hormone receptor (HR)-positive, HER2-negative advanced breast cancer." (PMID 26779371, 2015). "One recent study demonstrated that CEBPD directly inhibits expression of the tumor suppressor FBXW7, resulting in a consequent enhancement of mTOR/AKT/S6K1 signaling, which further suggests CEBPD is necessary for metastatic progression of mammary tumors." (PMID 26307680, 2015). "Pertinent for other types of breast cancer, increasing lines of evidence indicate that the PI3K/mTOR pathway is activated in TNBCs and/or BLBCs at the genetic, gene expression and protein levels." (PMID 24708766, 2014). "Cellular signaling pathways involving mTOR, PI3K and ERK have dominated recent studies of breast cancer biology, and inhibitors of these pathways have formed a focus of numerous clinical trials." (PMID 25170609, 2014).
breast cancer (continued). "The crosstalk between ER and HER2 activated mTOR through the PI3K/AKT pathway and then promoted the expression of FASN, contributing to malignant transformation in ER+/HER2+ breast cancer cells." (PMID 24866893, 2014). "Taken together, these results demonstrate that LIF activates the mTOR pathway, which contributes to the promoting effect of LIF on breast cancer metastasis." (PMID 24553191, 2014). "Our results showed that the combination of the mTOR and FASN inhibitors potently inhibited the growth and invasive capacity of three breast cancer cell lines, even at low concentrations." (PMID 24866893, 2014). "mTOR and VEGF seem to be a common pathway in breast cancer and in hemECs, involving enhanced angiogenesis." (PMID 26413184, 2014). "However breast cancer cells harboring PIK3CA mutations are selectively sensitive to mTOR allosteric and kinase inhibitors but not in breast cancer cells with loss of PTEN, suggesting that the functional consequences of these two mechanisms of mTOR activation are quite distinct." (PMID 25209360, 2014). "Given that NVP-BEZ235 is a poor inhibitor of AKT and PDK1, and inhibition of mTOR by AZD8055 prevents the activation of both AKT-T308 and AKT-S473, in our model AZD8055 is a better treatment for breast cancer." (PMID 25436981, 2014). "Blocking AKT activity by wortmannin or the expression of DN-AKT largely abolished the activation of mTOR by LIF, and more importantly, largely abolished the promoting effect of LIF on tumorigenesis and metastasis of breast cancer." (PMID 24553191, 2014). "The expression of p-mTOR and p-4E-BP1 were examined in the tumors of 83 cases of breast cancer patients." (PMID 25364442, 2014). "Multiple signaling pathways are known to drive breast cancer, including MAPK, Akt/mTOR, NF-κB and JAK/STAT." (PMID 25153725, 2014). "In this study, we highlight the clinical importance of factors downstream of mTOR, and show that mRNA expression of S6K2 and 4EBP1 are correlated and significantly related to poor outcome in four independent breast cancer cohorts." (PMID 24131622, 2013). "Third, DMC induced autophagy through mTOR inhibition, which is reminiscent with that reported with TZD PPARγ agonists in breast cancer cells." (PMID 23843889, 2013). "We have therefore studied PI3K/mTOR/Akt pathway activity in basal-like and luminal-like breast cancer xenografts, and the effect of the pan-Akt inhibitor MK-2206 and the dual PI3K/mTOR inhibitor BEZ235 in these models in vivo." (PMID 23448424, 2013). "In this study we demonstrate that hyperglycemia promotes breast cancer by altering leptin/IGF1R and AKT/mTOR signaling." (PMID 24260287, 2013). "This study establishes the mTOR effectors 4EBP1 and S6K2, as new potential clinical markers in breast cancer diagnostics and treatment prediction." (PMID 24131622, 2013). "Currently, several clinical trials are in progress investigating the effect of mTOR inhibitors (including everolimus, ridaforolimus, sirolimus, and temsirolimus) on HER2-positive breast cancer." (PMID 24069582, 2013). "Altogether, we propose the mTOR effectors 4EBP1 and S6K2 as new potential clinical markers in breast cancer." (PMID 24131622, 2013). "Whilst the mechanism for this is unclear, at the gene expression level we observed unexpectedly low levels of PI3K/mTOR pathway activation and increased levels of estrogen signaling in PIK3CA mutant breast cancers." (PMID 23301057, 2013). "Our previous studies have demonstrated that Akt and mTOR are constitutively phosphorylated in mammary tumors developed in MMTV-Aurora-A mice, suggesting that activation of Akt/mTOR is involved in Aurora-A's cell transformation." (PMID 23383195, 2013).
breast cancer (continued). "Mounting evidence suggests that Wnt induces mammary tumor formation from stem or progenitor cells via LRP5/6-mediated activation of ß-catenin and mTOR pathways." (PMID 24392029, 2013). "Using 4T1 or 67NR models of basal-like breast cancer, tumor growth was measured in mice treated with an FGFR inhibitor (dovitinib/TKI258), a PI3K/mTOR inhibitor (NVP-BEZ235) or a pan-ErbB inhibitor (AEE788) individually or in combination." (PMID 23343422, 2013). "The treatment of primary mammary tumor cells with specific mTOR inhibitors AZD8055 and Torin1, that target both mTOR complexes, attenuated mTOR activity and decreased expression of glycolytic enzymes." (PMID 23451056, 2013). "For example, oestrogen induced c-Src activation leads to 4E-BP phoshorylation through PI3K/mTOR pathway and consequently promotes translation of HIF-1 α in breast cancer cells." (PMID 24180592, 2013). "We can conclude that the main area of interest of using IGF-1R targeted agents in breast cancer is a combination strategy with endocrine treatment, HER2 and mTOR targeted agents." (PMID 22415797, 2012). "Over-expression of MTOR has also been suggested to be a poor prognostic factor in several human cancers, including RCC, lung cancer, breast cancer, laryngeal squamous cell carcinoma and biliary tract adenocarcinoma." (PMID 23209702, 2012). "Our results support that trastuzumab resistance mechanisms are related with deregulation of PTEN/PI3K/Akt/mTOR pathway, and/or EGFR and IGF1R overexpression in a subset of HER2-positive breast carcinomas." (PMID 22454081, 2012). "In summary, the results reported in this study help clarify why α-TEA is such a potent apoptotic agent in human breast cancer cell lines, and suggest potential utility for α-TEA in combination therapy with ERK and mTOR inhibitors." (PMID 21119656, 2011). "2-DG is also reported to decrease phosphorylation of mTOR and its downstream targets, p70S6k and 4E-BP1, in human breast cancer cells, leading to a reduced carcinogenic response and attenuated tumorigenicity." (PMID 21386904, 2011). "The PI3K catalytic subunit inhibitor BKM120, the mammalian target of rapamycin (mTOR) inhibitor RAD001 and the dual PI3K/mTOR inhibitor BGT226 were tested against ER-positive breast cancer cell lines before and after long-term estrogen deprivation (LTED)." (PMID 21362200, 2011). "Downregulation of IRS-1/PI3K pathways via JNK are critical for α-TEA and α-TEA+MEK or mTOR inhibitor-induced apoptosis in human MCF-7 and HCC-1954 breast cancer cells." (PMID 21119656, 2011). "The results define a signalling pathway in breast cancer cells whereby oestradiol induces a rapid protein–protein interaction of ERα-c-Src-PI3K, resulting in the activation of PI3K/AKT pathway leading to mammalian target of rapamycin (mTOR) phosphorylation." (PMID 21897387, 2011). "For example, a top hit in our screen, RPS6KB1, is downstream of mTOR and PI3K, two prominent signaling pathways in breast cancer with known direct inhibitors, rapamycin and LY294002, and that have been shown to sensitize cells to paclitaxel." (PMID 20576088, 2010). "Since TFRC expression is promoted by the Akt/mTOR pathway, this finding is in line with lapatinib-mediated Akt inhibition in HER2-overxpressing breast cancer cells." (PMID 20126311, 2010). "High expression of p-mTOR, p-P70S6K and p-4EBP1 correlate with poor outcome in glioblastoma, and p-4EBP1 was demonstrated to be a potential prognostic factor in breast cancer and an independent prognostic marker in ovarian cancer." (PMID 20338061, 2010). "p70S6 kinase is located downstream of PI3K/AKT/mTOR pathway, which is activated by HER2 receptors, insulin-like growth factor receptor and estrogen receptor in breast cancer." (PMID 18652687, 2008). "Our results show for the first time the genome-wide transcriptional consequences of PI3K/mTOR pathway and RPS6KB1 inhibitions in breast cancer, suggesting novel downstream targets for PI3K/mTOR pathway and p70S6 kinase." (PMID 18652687, 2008).
breast cancer (continued). "This is the first report demonstrating phosphorylation of PDK-1 is frequently elevated in breast cancer with concomitantly increased phosphorylation of downstream kinases, including AKT, mTOR, p70S6K, S6, and Stat3." (PMID 16288304, 2005). "To further confirm our investigation on increased phosphorylation in breast cancers, we have applied IHC staining on breast tumours fixed on TMA slides to examine the phosphorylation status of PDK-1, AKT, mTOR, p70S6K, S6, Stat3, and EGFR." (PMID 16288304, 2005). "In our both studies, however, similar findings were obtained regardless the source of breast cancer cells and thus confirmed the importance of PDK-1/AKT/mTOR/p70S6K activation in breast cancer." (PMID 16288304, 2005). "About 70% of breast cancers are ERα positive, while 15% to 30% of human breast tumors exhibit overexpression of HER-2 in clinical subgroups, and both of these factors raise HIF-α levels by boosting PI3K/Akt/mTOR signaling." (PMID 41614928, 2026). "Long-term CDK4i treatment, commonly used for luminal A breast cancer, activates alternative pathways, such as PI3K/AKT/mTOR, androgen receptor, and Hippo signaling, along with transcriptional reprogramming via noncoding RNAs, promoting the development of drug resistance." (PMID 41161384, 2025). "We demonstrated that the omega-10 fatty acids were able to modulate the expression and activation of EGFR receptor (epidermal growth factor receptor), AKT (protein kinase B), and mTOR (mammalian target of rapamycin) signaling pathway in MCF-7, MDA-MB-231, and BT-20 breast cancer cell lines." (PMID 40943166, 2025). "mTOR inhibitors, including rapamycin and the semi-synthetic derivative everolimus (EVE), are widely studied and applied in clinical trials for the treatment of cancer, showing specific beneficial effects in hormone receptor-positive (HR+) breast cancers." (PMID 40943647, 2025). "Similarly, in breast cancer cells, PI3K and mTOR inhibitors have been shown to reduce overall O-GlcNAcylation levels." (PMID 41203135, 2025). "The journal retracts the article titled “Tioconazole and Chloroquine Act Synergistically to Combat Doxorubicin-Induced Toxicity via Inactivation of PI3K/AKT/mTOR Signaling Mediated ROS-Dependent Apoptosis and Autophagic Flux Inhibition in MCF-7 Breast Cancer Cells.”, cited above." (PMID 40143217, 2025). "Articles cited in the review are from the Pubmed database from the years 2016–2025 (excluding articles that describe the first use of a given drug), selected based on the following keywords: drugs targeting PI3K/AKT/mTOR pathway breast cancer, TNBC therapy, nanoparticles in breast cancer." (PMID 41157256, 2025). "Interestingly, resistance to mTOR inhibition in breast cancer cells is mediated by hVPS34 and SGK3, defining an AKT independent mTOR activation pathway." (PMID 39663000, 2025). "Therefore, we sought to understand if PTEN C-terminal tail phosphorylation was altered in breast cancer cell lines after exposure to the PI3Kis BYL719 (PI3K), BEZ235 (pan-PI3K/mTOR), or GDC-0941 (pan-PI3K)." (PMID 40991650, 2025). "Further study demonstrated that targeting the Akt/mTOR pathway could control the protein expressions of cyclin D1 and CDK4, thus contribute to the development of drug resistance in breast cancer." (PMID 41460862, 2025). "In addition to its role in breast cancer cell growth, the PI3K/AKT/mTOR pathway was shown to regulate breast cancer bone metastasis." (PMID 39980332, 2025). "In breast cancer, particularly in the HER2-positive subtype, aberrant activation of the PI3K/AKT/mTOR and mitogen-activated protein kinase (MAPK/ERK) signaling pathways is frequently observed, promoting tumor cell proliferation, growth, migration, invasion, survival, and therapeutic resistance." (PMID 40943316, 2025).
breast cancer (continued). "In experimental models of ER+ breast cancer cell lines, prolonged endocrine deprivation led to the emergence of acquired resistance driven by increased PI3K signaling, with a proteomic analysis revealing enhanced phosphorylation of mTOR and Akt." (PMID 40244377, 2025). "To ensure the reliability of our data, we used in vitro A549 lung adenocarcinoma and MDA-MB-231 breast cancer triple-negative cell cultures to demonstrate the herb extract’s effects on PI3K and Akt enzymes and clarify how PI3K/Akt/mTOR mediation regulates TNFα, VEGFα, COX-2, MMP-2, and Caspase-3." (PMID 40179064, 2025). "Moreover, the PI3K/Akt/mTOR signaling pathway plays a significant role in breast cancer progression; protein expression and phosphorylation of AKT and mTOR in MDA‐MB‐231 upon GW405833 exposure were investigated." (PMID 39980332, 2025). "In addition, combination of PI3K/mTOR inhibitor Gedatolisib plus Palbociclib and endocrine therapy in women with HR+/HER2-negative advanced breast cancer was well tolerated with an acceptable safety profile." (PMID 40260297, 2025). "Examination of differential isoforms uniquely identified by BayesIso reveals PI3K/AKT/mTOR signaling and PTEN signaling pathways responsible, at least in part, for the development of breast cancer recurrence, and a large protein-protein interaction network associated with Jak-STAT and Wnt signaling." (PMID 39888956, 2025). "MiR-185-5p regulated processes like epithelial–mesenchymal transition (EMT) and invasion of breast cancer cells by targeting the receptor for advanced glycation end-products (RAGE), while miR-143-3p inhibits RAS/MEK/ERK and PI3K/AKT/mTOR pathways, which are significant in HER2 downstream signaling." (PMID 41471397, 2025). "Though OC-specific data are lacking, breast cancer studies show CTSD promotes mTOR-driven proliferation and M2 macrophage polarization, mechanisms compatible with the pro-metastatic TME features of our high-risk cohort." (PMID 40299498, 2025). "A phase I/Ib multicenter study has evaluated the MTD, safety, and pharmacokinetics of BEZ235, an oral dual PI3K/mTOR inhibitor, when used as monotherapy or in combination with trastuzumab in patients with advanced solid tumors, including HER2‐positive advanced breast cancer (aBC)." (PMID 40740483, 2025). "To test whether activation of the PAM signaling pathway is responsible for resistance in HER2-positive breast cancer induced by PPARG, we introduced Everolimus, an mTOR inhibitor widely used in studies of PAM signaling pathway inhibition." (PMID 40303293, 2025). "Studies have shown that the PI3K/Akt/mTOR signaling pathway is involved in metabolic processes such as glucose uptake and glycolysis, which are closely related to the occurrence and development of breast cancer, indicating that the PI3K/AKT/mTOR pathway should be targeted for the treatment of TNBC." (PMID 40076586, 2025). "Moreover, targeting PI3K/AKT/mTOR signaling pathway with a combination therapy of PI3K inhibitors and trastuzumab to treat HER2-positive breast cancer can ameliorate resistance and restore apoptotic effects." (PMID 40227634, 2025). "Additionally, PA exerts anti-cancer effects by interfering with key signaling cascades; for instance, it blocks the NF-κB/ERK/mTOR pathway and inhibits MMP-9 and FAK expression in growth factor-stimulated breast cancer cells." (PMID 40535769, 2025). "In breast cancer—particularly triple−negative breast cancer—the Notch3/mTOR/HIF−1 signaling axis enhances glycolysis and thereby supports cancer stem cell survival and chemoresistance." (PMID 41050674, 2025). "In contrast, in ER-breast cancer, the inhibition of PI3K/mTOR activates Wnt/β-catenin signaling." (PMID 40804731, 2025). "In MCF-7 human breast cancer cells, zinc treatment of ZIP7-overexpressing cells significantly enhanced ZIP7-mediated zinc release, leading to the activation of downstream signaling pathways including PI3K/Akt, MAPK, and mTOR." (PMID 40943601, 2025).